ROS1 (ROS proto-oncogene 1, receptor tyrosine kinase)
Diseases named in the same sentence as ROS1 in open-access papers (continued):
Sharing a sentence is not in itself a finding about the gene and the disease.
sarcoma (11 papers, 2013 to 2025). A usually aggressive malignant neoplasm of the soft tissue or bone. "These included ALK, BRAF, FGFR1–4, NTRK1–3, RET, and ROS1 kinase fusions in a wide range of sarcoma histologies, including IMT (62.1%), MPNST (4.9%), UPS of bone (4.3%), extraskeletal osteosarcomas (4%), UPS (3.6%), sarcoma NOS (3.8%), and LMS (1.9%)." (PMID 35705558, 2022). "Another attractive therapeutic target is ROS1, a proto-oncogene receptor tyrosine kinase; we found circROS1 to be specifically identified in the sarcoma." (PMID 31446897, 2019). "Subsequent analysis of this sample showed ROS1 expression to be 50-fold higher than the median of all sarcoma samples, supporting the existence of a promoter fusion that deregulated ROS1 expression." (PMID 30918253, 2019). "Notably, among various high-grade sarcoma subtypes, tyrosine kinase fusions—specifically ROS1 and NTRK3—have been detected only in LMS cases." (PMID 40868997, 2025). "To determine whether ROS1 rearrangements recurred in angiosarcomas or other sarcoma subtypes, we performed the break-apart FISH assay on two tissue microarrays (TMA) containing 280 specimens representing 36 diverse sarcoma and soft tissue tumor diagnoses." (PMID 23637631, 2013). "Nevertheless, the finding of elevated ROS1 expression in angiosarcomas, relative to other sarcoma subtypes, suggests that ROS1 might play a broader role in angiosarcoma pathogenesis." (PMID 23637631, 2013). "In a recent large study of sarcoma, CGP identified potentially actionable kinase fusions (including NTRK1‐3, ALK, BRAF, FGFR1‐4, RET, and ROS1) in 2.6% of patients." (PMID 38925616, 2024). "Notably, for one sarcoma sample, targeted RNAseq was unable to identify a fusion gene, despite previous FISH analysis reporting a chromosomal rearrangement involving ROS1." (PMID 30918253, 2019). "No additional ROS1 rearrangements were identified in other sarcoma and soft tissue tumor subtypes." (PMID 23637631, 2013). "For example, not all BCOR-rearranged sarcomas are positive for BCOR on IHC, and a subset of IMTs are negative for ALK on IHC because they harbor alternative ROS1 or RET gene fusions instead of an ALK fusion." (PMID 38137051, 2023).
Pleural effusion (10 papers, 2018 to 2025). The presence of an excessive amount of fluid in the pleural cavity. "Following disease progression on lorlatinib, next-generation sequencing analysis of pleural effusion identified an acquired ROS1 L2086F resistance mutation, accompanied by a concurrent mTOR mutation and FGFR3 gene amplification." (PMID 40826797, 2025). "NGS analysis of pleural effusion revealed a complex resistance profile, including the original CD74-ROS1 fusion, an acquired ROS1 L2086F resistance mutation, an mTOR (p.E2419K) mutation, and FGFR3 gene amplification." (PMID 40826797, 2025). "Sixty‐six patients were tested for ROS1 fusion using only liquid biopsies, including 40 cases of plasma, 25 cases of malignant pleural effusion, and one case with both plasma and pleural effusion samples tested." (PMID 32871626, 2020). "The molecular retesting of the tumour cells obtained from the recurrent pleural effusion revealed the absence of the ROS1 translocation, whereas the EGFR and HER2 mutations were still present." (PMID 38891886, 2024). "Case #29, positive for ROS1 rearrangement via FISH on a pleural biopsy collected in 2017, was also tested on a cell block obtained from a pleural effusion." (PMID 36612287, 2022). "Pleural effusion was the next most common presentation with 9 (40%) and 231(45%) in the ROS1-positive and negative cohorts, respectively." (PMID 30915158, 2019).
pancreatic cancer (9 papers, 2013 to 2025). "Of note, ROS1 mutations were associated with response to anti-ROS1 inhibitors, such as Lorlatinib in pancreatic cancer." (PMID 35011716, 2022). "In a study sequencing 336 pancreatic cancer specimens, potentially actionable targets were identified in 26% of cases, including alterations in ERBB2, BRCA1 or BRCA2, BRAFV600E, ROS1, and ALK1." (PMID 40227779, 2025). "In our study, ROS1 fusions were also detected at similar frequency as previously reported ROS1+ NSCLC tumors of approximately 2% in other major tumors such as breast and pancreatic cancers." (PMID 37853341, 2023). "When applied to a large collection of published pancreatic cancer samples (n = 803), Arriba identified a variety of driver fusions, many of which affected druggable proteins, including ALK, BRAF, FGFR2, NRG1, NTRK1, NTRK3, RET, and ROS1." (PMID 33441414, 2021).
anaplastic large cell lymphoma (8 papers, 2016 to 2024). Anaplastic large cell lymphoma (ALCL) is a rare and aggressive peripheral T-cell non-Hodgkin lymphoma, belonging to the group of CD30-positive lymphoproliferative disorders, which affects lymph nodes and extranodal sites. "We and others have recently demonstrated that a small subset of systemic (<5%) and cutaneous (~20%) Anaplastic Large Cell Lymphomas (ALCL) bears ROS1 or TYK2 fusions." (PMID 26943776, 2016). "Sixty-four children with solid tumors or anaplastic large-cell lymphoma (ALCL) enrolled on a phase 1/2 trial of the ALK, MET and ROS1 inhibitor, crizotinib, had pharmacokinetic sampling after the first dose (n = 15) or at steady state (n = 49)." (PMID 28032129, 2017). "Crizotinib is an ALK and ROS1 inhibitor approved for NSCLC and anaplastic large cell lymphoma." (PMID 38345654, 2024).
colon cancer (8 papers, 2013 to 2023). "In line with this evidence, we have shown that HGF, which can be produced by tumor‐associated fibroblasts, induced entrectinib resistance in NTRK1 rearranged colon cancer and ROS1 rearranged NSCLC models." (PMID 36416133, 2023). "In addition, METex14del occurs exclusively to ALK, ROS1, NTRK1, NTRK3 or RET fusions indicating METex14del is likely a driver mutation and defines a unique molecular subset of gastric and colon cancers." (PMID 26375439, 2015). "FuSiOn identified ten kinases (BMP2K, DCLK3, LIMK2, MAP2K5/MEK5, MAP3K3/MEKK3, ROS1, SIK2, TAOK2, ULK1, and ULK2) whose depletion mimicked the phenotypic effect of p62 depletion in HCT116 colon cancer cells." (PMID 33101709, 2020). "Similarly, five genes including TOP2A, REL, SHH, ROS1, and CHEK2 in colon cancer gene network and three genes including RBL1, MAPK9, and PIK3CA in adenocarcinoma of lung gene network are selected." (PMID 29670664, 2018).
lymphoma (6 papers, 2021 to 2025). A malignant (clonal) proliferation of B- lymphocytes or T- lymphocytes which involves the lymph nodes, bone marrow and/or extranodal sites. "In an expanded molecular cohort of subjects compiled by three commercial vendors, the detection of ALK or ROS1 rearrangements outside of NSCLC or lymphoma was rare." (PMID 35233056, 2022). "In our study, we found ECOG score 3–4 was closely associated with mutations in MYD88, MALT1, and ROS1, which suggested that ECOG might be associated with lymphoma heterogeneity." (PMID 35865478, 2022). "A review of over 30,000 tumors excluding those with NSCLC or lymphoma from two of these commercial vendors identified ALK rearrangements in 1/1,000 specimens and ROS1 rearrangements in 4/10,000 specimens." (PMID 35233056, 2022).
small cell lung carcinoma (6 papers, 2013 to 2025). Small cell lung cancer (SCLC) is a highly aggressive malignant neoplasm, accounting for 10-15% of lung cancer cases, characterized byrapid growth, and early metastasis. "Patient-derived models generated from autopsy retained features consistent with small cell lung cancer and demonstrated resistance to ROS1 inhibitors." (PMID 32802958, 2020). "We observed that neither the resistant patient sample nor the HCC78-TR cells had undergone ROS1 kinase domain mutation, ROS1 fusion gene amplification, EMT, or conversion to small cell lung cancer histology." (PMID 24349229, 2013). "Small cell lung cancer (SCLC) transformation has been reported in 3–14% of patients treated with first- and second-generation EGFR TKI, and in 5–20% of those receiving Osimertinib and has also been observed in ALK- and ROS1-rearranged tumors, suggesting that it is independent of TKI class." (PMID 41228269, 2025).
thyroid cancer (6 papers, 2018 to 2024). "ROS1 inhibitors such as Entrectinib have also been used in one patient with ROS1 mutation thyroid carcinomas with liver metastasis and showed efficacy." (PMID 37510219, 2023). "Thyroid cancers with BRAF mutations and ROS1 fusion resulted in the highest frequency of recommendations." (PMID 36251535, 2023). "Currently, two non-selective HGFR TKIs have been approved: crizotinib (first approved in 2011) for ALK- and ROS1-positive NSCLC and cabozantinib (First approved in 2016) for thyroid cancer and kidney cancer." (PMID 37543570, 2023).
breast tumor (5 papers, 2019 to 2025). "For example, the proto-oncogene ROS1 encodes a receptor tyrosine kinase (ROS1), and a preclinical study of CDH1 synthetic lethality interactions has identified ROS1 as a potential target in breast tumor cells with CRISPR/Cas9-engineered CDH1 mutations." (PMID 39941785, 2025). "The CD74-ROS1 fusion gene combined an exon 7 of CD74 and an exon 34 of ROS1, and the ROS1 protein was overexpressed, driven by this fusion oncogene in breast tumor tissues." (PMID 34051833, 2021). "The Authors showed that ROS1 inhibition in E‐cad‐defective breast tumour cell lines and patient‐derived breast tumour xenografts resulted in tumour cell death." (PMID 32301282, 2020).
gastric adenocarcinoma (5 papers, 2015 to 2024). "Moreover, gastric adenocarcinomas expressing ROS1 by immunohistochemistry tended to present with differentiated tumors and lower lymph node status." (PMID 26475437, 2015).
leukemia (5 papers, 2018 to 2022). A malignant (clonal) hematologic disorder, involving hematopoietic stem cells and characterized by the presence of primitive or atypical myeloid or lymphoid cells in the bone marrow and the blood. "In our study, we found NOTCH2, FANCA, BCR, and ROS1 were significantly mutated in 109 Chinese patients with leukemia." (PMID 32638549, 2020). "Mutational analysis was used to map the genetic variants in leukemia, and found that the highest mutations occurred in PDE4DIP, followed by NOTCH2, FANCA, BCR, and ROS1 in almost all leukemia patients." (PMID 32638549, 2020). "Previously, NOTCH2, FANCA, BCR, and ROS1 have been described to play an important role in leukemia." (PMID 32638549, 2020).
viral infection (5 papers, 2013 to 2025). "For instance, in Arabidopsis thaliana plants infected with beet severe curly top virus, the expression of ROS1 is significantly upregulated, highlighting its importance in the plant’s response to viral infection." (PMID 40751127, 2025). "Despite lower fitness of the marked virus, Ros1 is therefore a viable alternative marker for tracking viral infection in plants." (PMID 24022073, 2013). "Antirrhinum majus Rosea1 (Ros1) is an MYB-related transcription factor that induces anthocyanin biosynthesis in plant tissues, and has been shown to be suitable for visual tracking of virus infection in plants." (PMID 24022073, 2013).
angiosarcoma (4 papers, 2013 to 2023). A malignant tumor arising from the endothelial cells of the blood vessels. "This is particularly crucial for malignancies that are often resistant to standard treatments such as angiosarcoma, or frequently harbor actionable mutations such as ROS1 fusions." (PMID 30719217, 2019). "Specifically, a small cohort of angiosarcoma project dataset in cBioportal showed homodeletion of ROS1 in two out of 12 sequenced patients." (PMID 30719217, 2019). "By FISH analysis, ROS1 rearrangements appear to be infrequent in angiosarcoma (and in another endothelial-derived tumor, epithelioid hemangioendothelioma)." (PMID 23637631, 2013). "We suggest that testing for ROS1 fusion and, if positive, treatment with a targeted therapy could be considered at the time of diagnosis for patients with angiosarcoma." (PMID 30719217, 2019). "Notably, some of these fusions (e.g. CEP85L/ROS1 in angiosarcoma) represent the first for that cancer type and thus provide important new biological insight." (PMID 23637631, 2013). "Thus, in all we observed ROS1 rearrangement in 1 of 34 (∼3%) angiosarcomas and 1 of 20 (5%) EHE cases." (PMID 23637631, 2013). "In addition to including various vascular endothelial markers (ECSCR, TIE1, CD34, CDH5, ESAM), the angiosarcoma gene signature also included ROS1, supporting a possible broader role of ROS1 in the pathogenesis of this disease." (PMID 23637631, 2013). "Of 33 evaluable angiosarcoma and 20 epithelioid hemangioendothelioma (EHE; a related diagnosis) cases, one EHE case (EHE10) exhibited rearrangement at the ROS1 locus." (PMID 23637631, 2013). "The ROS1 rearrangement (CEP85L/ROS1), to our knowledge, represents the first gene fusion described in angiosarcoma." (PMID 23637631, 2013). "However, only the primary angiosarcoma specimen, AS1, exhibited a prominent and highly significant (P<10−27) expression transition, with the predicted breakpoint corresponding to known rearrangements of ROS1 in other malignancies." (PMID 23637631, 2013). "Although ROS1 rearrangements appeared to be relatively uncommon, we hypothesized that ROS1 might nonetheless play a more general role in angiosarcoma pathogenesis, even in cases without rearrangement." (PMID 23637631, 2013).
astrocytoma (4 papers, 2015 to 2022). "GOPC/FIG was initially named following its discovery as a ROS1 fusion partner in a patient-derived astrocytoma cell line." (PMID 30719217, 2019).
chronic myeloid leukemia (4 papers, 2021 to 2025). "This includes BCR-ABL in chronic myelogenous leukemia (CML), ALK and ROS1 kinase fusions in non-small cell lung cancer, as well as TRK fusions in solid cancers." (PMID 38110872, 2023).
heart failure (4 papers, 2022 to 2025). Inability of the heart to pump blood at an adequate rate to meet tissue metabolic requirements. "In a case of NSCLC with ROS1 rearrangement, the patient developed drug-induced heart failure after treatment with entrectinib, and the symptoms improved after drug discontinuation." (PMID 38357305, 2024). "We report a case of NSCLC with ROS1 rearrangement where the patient developed drug-induced heart failure after receiving entrectinib." (PMID 36605067, 2022). "Of note, crizotinib also inhibits other kinases, including MET and ROS1, which may contribute to its toxicity profile which includes heart failure, arrhythmias, and conduction abnormalities." (PMID 40828781, 2025).
Hypertension (4 papers, 2019 to 2025). The presence of chronic increased pressure in the systemic arterial system. "Throughout the follow‐up period, ROS1 rearrangements and hypertension were independent TE risk factors." (PMID 40751559, 2025). "Over the entire follow‐up period, ROS1 fusions and hypertension were identified as independent risk factors for TEs." (PMID 40751559, 2025). "Co-morbidities were matched between the two cohorts with 7(31%) having hypertension and 4(18%) having diabetes mellitus in the ROS1-positive group and 123(24%) and 95 (18%), respectively, in the ROS1-negative group." (PMID 30915158, 2019).
Non-squamous Non-small Cell Lung Cancer (4 papers, 2020 to 2023). "ROS proto-oncogene 1 (ROS1) rearrangements are reported in about 1–2% of non-squamous non-small-cell lung cancer (NSCLC)." (PMID 34884672, 2021). "In non-squamous non-small-cell lung cancer, 9/15 were all EGFR, ALK, and ROS1 wild-type." (PMID 33042826, 2020).
prostate carcinoma (4 papers, 2019 to 2025). A carcinoma that arises from epithelial cells of the prostate gland. "Cabozantinib is an orally bioavailable small molecule inhibitor of c-Met, RET, ROS1, Alk, VEGFR2, and TRK receptors with approved uses for the treatment of metastatic medullary thyroid cancer, prostate cancer and advanced renal cell carcinoma." (PMID 30885237, 2019). "Furthermore, we plan to develop a similar approach toward other gene fusions, such as ROS1, RET, and NTRK in NSCLC, but also gene fusions identified in other solid cancers, such as TMPRSS2-ERG in prostate cancer, EVT6-NTRK3 in secretory breast carcinoma etc." (PMID 37016288, 2023). "Although some patients were treated for advanced HER2+ and triple‐negative breast cancer, advanced prostate cancer, and ALK and ROS1 NSCLC, experts deemed them unrepresentative in terms of healthcare resource utilization." (PMID 40740130, 2025).
renal cell carcinoma (4 papers, 2019 to 2025). "In the phase II eligible population, the ORR was 86% among 14 patients with ROS1-rearranged disease (all but one with NSCLC), and an ORR of 57% among seven patients with ALK-rearranged tumors, including NSCLC, renal cell carcinoma, and CRC." (PMID 38938274, 2024).
soft tissue sarcoma (4 papers, 2019 to 2022). A malignant neoplasm arising from muscle tissue, adipose tissue, blood vessels, fibrous tissue, or other supportive tissues excluding the bones. "In TCGA sarcoma dataset (265 patients with soft tissue sarcomas and 9 patients with nerve sheath tumors), we identified concurrent gene amplification or gain of ROS1 and GOPC involving 6q22.1 in 53 (21%) of the patients." (PMID 30719217, 2019). "We then queried the MSK-IMPACT clinical sequencing cohort and cBioportal datasets, demonstrating the previously unknown prevalence of ROS1-GOPC fusions in soft tissue sarcomas and hepatobiliary cancers." (PMID 30719217, 2019). "Notably, Kaplan–Meier survival estimate showed a poor overall survival in both soft tissue sarcoma and hepatocellular carcinoma patients with ROS1 and GOPC gain/amplification." (PMID 30719217, 2019). "To further explore the incidence of ROS1 and GOPC concurrent alterations in primary hepatobiliary tumors and soft tissue sarcomas, we queried available datasets in cBioportal." (PMID 30719217, 2019). "This database analysis highlights the previously unknown involvement of ROS1 and GOPC copy number alterations in soft tissue sarcomas and hepatic cancers." (PMID 30719217, 2019). "Although this is the first report of ROS1-GOPC fusion in HAS, database analysis highlights the previously unknown frequency of ROS1 and GOPC molecular alterations in soft tissue sarcomas and hepatic cancers." (PMID 30719217, 2019). "The approvals based on early phase studies regarded especially targeted therapy (anti ROS1, anti ALK, and anti-RET) in NSCLC and some rare disease (medullary and non-medullary thyroid cancer, soft tissue sarcoma, GIST)." (PMID 35205637, 2022).
brain tumor (3 papers, 2018 to 2023). "Therefore, to treat ROS1-fusion-positive brain tumors more effectively and safely, exploring novel therapeutic target(s) of ROS1-fusion-positive tumors other than the C-terminal activation loop of ROS1 is warranted." (PMID 38201436, 2023). "We hypothesized that ZCCHC8, as a 5′ fusion partner, might drive (over)expression of the ROS1 transcript and compared the ROS1 expression with that of all other brain tumor samples in our cohort." (PMID 35085008, 2022). "All brain tumors, with the exception of a teratoma sample, show lower ROS1 expression, supporting the validity of the ZCCHC8-ROS1 fusion." (PMID 35085008, 2022).
gastrointestinal stromal tumor (3 papers, 2015 to 2019). "For example, imatinib has been repositioned to inhibit KIT and PDGFRA in gastrointestinal stromal tumors and crizotinib has been repositioned to inhibit ROS1 in ROS1-fusion NSCLC patients." (PMID 26681397, 2015).